COL18A1 (collagen type XVIII alpha 1 chain)
Diseases named in the same sentence as COL18A1 in open-access papers (continued):
Sharing a sentence is not in itself a finding about the gene and the disease.
bladder cancer (3 papers, 2014 to 2022). "In addition, the upregulated expression of COL18A1 was found in bladder cancer patients with tumor stages T1 and T2, which may be involved in the progression of bladder cancer by affecting extracellular matrix-receptor interactions and adhesion sites." (PMID 35149954, 2022).
collagenopathy (3 papers, 2022 to 2025). "Bilateral RRD was only seen in collagenopathies/vitreoretinopathies with COL2A1 (n = 2, 33.3%), COL11A1 (n = 1, 16.7%), COL18A1 (n = 1, 16.7%) and FBN1 (n = 2, 33.3%) genotypes." (PMID 41465105, 2025). "If collagenopathies (COL2A1, COL11A1, COL18A1) and Marfan syndrome are removed, this figure (n = 3/401, 0.7%) remains 70× the population risk." (PMID 41465105, 2025).
metastatic tumor (3 papers, 2011 to 2022). "The results showed that CAFs in metastatic tumors expressed high levels of KRT15, FABP4, S100A8, and COL18A1 and were associated with high enrichment of vasculature development, cell population proliferation, and epithelial cell differentiation." (PMID 36569924, 2022).
nephritis (3 papers, 2014 to 2025). Inflammation of renal tissue. "Fabp4, Gsn, Il6st, and Ly6e, were associated with nephritis and Col18a1, Prom1, and Scd1 with renal cell carcinoma." (PMID 25409434, 2014).
angle-closure glaucoma (2 papers, 2021 to 2024). The sudden increase of intraocular pressure, resulting in pain and an abrupt decrease in visual acuity. "While the role of COL18A1 in POAG is yet to be established, mutation in this protein is associated with angle closure glaucoma." (PMID 33808966, 2021).
epilepsy (2 papers, 2017 to 2024). A brain disorder characterized by episodes of abnormally increased neuronal discharge resulting in transient episodes of sensory or motor neurological dysfunction, or psychic dysfunction. "In the family 1, which presented with epilepsy, developmental delay (DD), sleep disturbance, and aggressive behavior, a homozygous splice site variant, c.1339–6 C > T, in the COL18A1 gene was detected." (PMID 38783254, 2024). "Thus, the current study provides evidence that the COL18A1 variant might cause ASM-resistant epilepsy and comorbidities." (PMID 38783254, 2024). "Using WES, homozygous pathogenic variants in the COL18A1, UFSP2, ZFYVE26 and ATP13A2 genes were detected to cause ASM-resistant epilepsy and its comorbid conditions in four Pakistani families." (PMID 38783254, 2024).
hepatic carcinoma (2 papers, 2012 to 2021). "Wu et al36 have suggested that COL18A1 rs7499, located in the 3’‐UTR region, increases the risk of hepatocellular carcinoma in Chinese Han population by negatively working in the binding site for has‐mir‐328." (PMID 33296124, 2021). "Therefore, COL18A1 is associated with liver fibrosis via regulating the expression of EST COL18A1 is also related to hepatic carcinoma by EST." (PMID 33296124, 2021).
Hepatic fibrosis (2 papers, 2021 to 2025). The presence of excessive fibrous connective tissue in the liver. "Type XVIII collagen, encoded by COL18A1, can increase before and during the fibrotic stages of liver fibrosis." (PMID 33296124, 2021). "Classical fibrotic mediators and markers (including Tgfb1, Timp1, and Vcam1), collagen of the ECM (including Col4a1, Col4a2, Col16A1, and Col18a1) and cell surface adhesion and signaling integrin (Itga2, Itga5) were found to be differentially expressed in the enriched hepatic fibrosis pathways." (PMID 39747668, 2025). "Musso et al44 have reported the relationship between COL18A1 and liver fibrosis." (PMID 33296124, 2021).
liver cancer (2 papers, 2020 to 2021). An epithelial or non-epithelial malignant neoplasm that arises from the liver. "Besides, the relationship between COL18A1 polymorphisms and liver cancer is also reported." (PMID 33296124, 2021). "Based on these relationships, both COL18A1 and its product, EST, are considered as targets of liver cancer due to their function of restricting of endothelial proliferation and inhibiting the growth and metastasis of tumors." (PMID 33296124, 2021).
myocardial infarction (2 papers, 2018 to 2024). Gross necrosis of the myocardium, as a result of interruption of the blood supply to the area, as in coronary thrombosis. "Circulating endostatin produced by the cleavage of COL18A1 is positively associated with several age-associated diseases, including chronic obstructive pulmonary disease and myocardial infarction." (PMID 38645061, 2024). "Further study is needed to investigate the influence of COL18A1-specific gene knockdown on the healing process after myocardial infarction." (PMID 29509663, 2018). "A knockdown of the COL18A1 gene in the myocardial infarction model rats using small interference RNA (siRNA) worsened the cardiac function concomitant with wall thinning and decreased the α-SMA-positive myofibroblasts and scar formation compared with that of control siRNA-injected rats." (PMID 29509663, 2018).
Obesity (2 papers, 2023). Accumulation of substantial excess body fat. "Multiple single-nucleotide polymorphisms (SNP) in COL18A1 are associated with obesity in T2D and with circulating lipid contents." (PMID 37239083, 2023). "Expression of COL18A1 has been associated with human adipocyte differentiation and susceptibility to obesity, and preclinical work demonstrates that knockout of COL18A1 is associated with a reduction in adiposity in murine models." (PMID 37630778, 2023).
psoriasis (2 papers, 2023 to 2025). An autoimmune condition characterized by red, well-delineated plaques with silvery scales that are usually on the extensor surfaces and scalp. "Thus, this study demonstrated an association between polymorphisms in the SLC19A1 rs1051266 and COL18A1 rs9977268 genes and the need to switch from methotrexate to biologic therapy in patients with moderate-to-severe psoriasis." (PMID 41590498, 2025).
retinal dystrophies (2 papers, 2024). "Whole exome sequencing revealed no additional potentially pathogenic variants in COL18A1 or in any other genes associated with retinal dystrophies and/or connective tissue disorders in these families." (PMID 39457419, 2024).
Stickler syndrome (2 papers, 2007 to 2025). Stickler syndrome is an inherited vitreoretinopathy characterized by the association of ocular signs with more or less complete forms of Pierre-Robin sequence, bone disorders, and sensorineural deafness (10% of cases). "RRD is related to pathological mechanical changes in the vitreoretinal interface (e.g., posterior vitreous detachment, PVD; lattice degeneration, 30–46% of RRD); thus, genetic variants in collagen genes (e.g., COL2A1, COL11A1, COL18A1) are logically implicated in Stickler syndrome." (PMID 41465105, 2025). "Among these are collagen, type XVIII, alpha 1 (COL18A1) for Knobloch and collagen, type II, alpha 1 (COL2A1) for Stickler syndrome." (PMID 17653045, 2007).
viral infection (2 papers, 2023 to 2025). "The top 4 were “Cell matrix adhesion and organization” (COL6A1, COL6A2, COL18A1, JAM2, ADAMTS5 and POFUT2), “Immune/virus infection response” (MX1 and MX2), “Histone modification and chromatin remodeling” (NRIP1) and “Glycerolipid and lipid metabolism” (AGPAT3)." (PMID 38095646, 2023).
alopecia (1 paper, 2021). Hair loss usually from the scalp. "Furthermore, alopecia areata appeared in the midline of the occipital regions of three patients with COL18A1 mutations." (PMID 34249907, 2021).
alopecia areata (1 paper, 2021). Loss of scalp and body hair involving microscopically inflammatory patchy areas. "In the present study, pathogenic mutations were detected in six early onset high myopia patients with midline alopecia areata, and the causative genes included not only the COL18A1 gene but also the LAMA1 gene." (PMID 34249907, 2021).
atherosclerosis (1 paper, 2020). A disease characterized by the build-up of fatty material and calcium deposition in the arterial wall resulting in partial or complete occlusion of the arterial lumen. "The COL18A1 gene is associated with neovascularization and vascular permeability in atherosclerosis in mice and is also reported to inhibit angiogenesis and tumor growth." (PMID 33240310, 2020).
autism (1 paper, 2024). Persistent deficits in social interaction and communication and interaction as well as a markedly restricted repertoire of activity and interest as well as repetitive patterns of behavior. "Previously, compound heterozygous COL18A1 variants were identified in patients with CNS defects such as autism and developmental delay without ocular malformations." (PMID 38783254, 2024). "However, García-Prieto and colleagues reported a patient carrying pathogenic COL18A1 variants with brain defects such as autism and DD, without other significant ocular and occipital defects." (PMID 38783254, 2024).
cardiomyopathy (1 paper, 2022). A disease of the heart muscle or myocardium proper. "Mice lacking COL15A1 and COL18A1 genes present impaired heart function phenotypes; specifically, Col15a1(-/-) knockout leads to a complex cardiac phenotype and predisposes mice to cardiomyopathy." (PMID 36292100, 2022).
cataract (1 paper, 2021). Partial or complete opacity of the crystalline lens of one or both eyes that decreases visual acuity and eventually results in blindness. "Congenital cataracts were recorded in one patient (20204) with COL18A1 mutant." (PMID 34249907, 2021).
Cerebellar atrophy (1 paper, 2022). Cerebellar atrophy is defined as a cerebellum with initially normal structures, in a posterior fossa with normal size, which displays enlarged fissures (interfolial spaces) in comparison to the foliae secondary to loss of tissue. "Brain MRI revealed cerebellar atrophy, and the c.3523_3524delCT mutation in the COL18A1 gene was identified through whole-exome sequencing." (PMID 36614931, 2022).
cerebral small vessel disease (1 paper, 2025). Cerebral small vessel disease is the term currently used to pathological processes that affect the brain parenchymal circulation (arterioles, capillaries, and veins). "In patients with cerebral small vessel disease (CSVD), COL18A1 is markedly upregulated in the vasculature, pointing to a potential link between vascular remodeling and CBF regulation in MDD." (PMID 41221349, 2025).
COVID-19 (1 paper, 2023). A disease caused by infection with severe acute respiratory syndrome coronavirus 2. "The most changed components of BM included laminins (LAMB2, LAMA2, LAMC3, LAMB1, LAMC1, and LAMA5) and proteoglycans (COL18A1, HSPG2, and AGRN), with some BM specific collagens (IV, VIII, XVIII, and V collagens) remaining in COVID-19 brains, as compared with the control brains." (PMID 36609561, 2023).
diffuse large B-cell lymphoma (1 paper, 2020). "Finally, certain lymphoproliferative diseases are also associated with expression of COL6A1, COL18A1, MMP3 and TIMP1, and a subset of patients with diffuse large B cell lymphoma and adverse prognosis show decreased expression of POSTN, SPARC, COL1A1, COL3A1,CSTK, MMP9 and LAMB3." (PMID 33379263, 2020).
dyslipidemia (1 paper, 2020). "When we studied the effect of dyslipidemia (DLP), only one gene was significantly reduced in SAT, COL18A1." (PMID 33022994, 2020).
Encephalocele (1 paper, 2023). A neural tube defect characterized by sac-like protrusions of the brain and the membranes that cover it through openings in the skull. "However, while encephalocele arises as part of some syndromes in which causative genes have been identified, such as Meckel syndrome (multiple genes) and Knobloch syndrome type 1 (COL18A1), in most cases, the genetic basis is not known." (PMID 37364051, 2023).
gliosarcoma (1 paper, 2019). A rare histological variant of glioblastoma (WHO grade IV) characterized by a biphasic tissue pattern with alternating areas displaying glial and mesenchymal differentiation (WHO). "More interestingly, we found several genes highly up-regulated in gliosarcoma, including the genes encoding proteins putatively related to differentiation: UNC5B, a metallopeptidase (ADAMTS4) and a collagen COL18A1, in comparison to GBMs (log2 fold change)." (PMID 30818875, 2019).
heart failure (1 paper, 2022). Inability of the heart to pump blood at an adequate rate to meet tissue metabolic requirements. "In the heart, microarrays and qPCR validation have revealed a robust increase in expression of Col18a1 in the LV in a rat model of postinfarction heart failure." (PMID 36388115, 2022).
Hepatic steatosis (1 paper, 2025). Steatosis is a term used to denote lipid accumulation within hepatocytes. "In participants with severe hepatic steatosis (n = 43), subgroup analysis showed increased COL18A1, AFM, PRG4, and INHBE and decreased C4A and APOA1." (PMID 41354933, 2025).
hypertriglyceridemia (1 paper, 2010). A laboratory test result indicating elevated triglyceride concentration in the blood. "The hypertriglyceridemia and reduction in plasma and endothelium-bound Lpl in Col18a1−/− mice prompted further evaluation in humans with Col18-deficiency." (PMID 21085708, 2010). "In contrast, Col18a1−/− mice develop hypertriglyceridemia due to altered extrahepatic clearance triglyceride-rich lipoproteins." (PMID 21085708, 2010). "However, Gpihbp1−/− mice differ significantly from Col18a1−/− mice in the extent of hypertriglyceridemia and localization of Lpl in tissues." (PMID 21085708, 2010).
keloid (1 paper, 2007). An irregularly shaped, elevated mark on the skin caused by deposits of excessive amounts of collagen during wound healing. "We validated the expression of ECM-2, ESM1, THBS1, FBLN5 and COL18A1 in keloids, incisional scars and adhesions and the analysis indicated an elevated expression of ECM2, THBS1 and FBLN5 in keloid/incisional scars and COL18 in peritoneal adhesions as compared to leiomyomas." (PMID 17718906, 2007).
lung fibrosis (1 paper, 2025). "These proteins form a network that governs ECM stability and late-stage upregulation of COL18A1 and downregulation of ELN, both of which highlight a unique pattern of structural vulnerability to lung fibrosis and reduced elasticity in the aging lung." (PMID 40664891, 2025).
male infertility (1 paper, 2017). The inability of the male to effect fertilization of an ovum after a specified period of unprotected intercourse. "Conversely, some hypermethylated genes (such as, DENND2D and LOC401127) and hypomethylated genes (such as, HLA-DPA1 and COL18A1) have not previously been associated with male infertility, which may provide novel insight into the etiology of idiopathic SO." (PMID 28553232, 2017).
meningocele (1 paper, 2014). A congenital abnormality in which the meninges protrude through a defect in the spinal column or the cranium. "Retrospective evaluation of additional clinical data upon identification of the mutation in COL18A1 revealed that the patient had a meningocele surgically removed at 6 weeks of age." (PMID 25392994, 2014).
osteomyelitis (1 paper, 2022). An acute or chronic inflammation of the bone and its structures due to infection with pyogenic bacteria. "Between the two gene subtypes, the expression of 2 collagen-related genes was significantly different, among which COL8A2 and COL18A1 were all highly expressed in gene cluster A osteomyelitis." (PMID 36544487, 2022). "Between the two gene subtypes, the expression of 3 collagen-related genes was significantly different, among which COL4A1, COL8A2 and COL18A1 were all highly expressed in gene cluster A osteomyelitis." (PMID 36544487, 2022). "The results suggested that both COL4A1 and COL18A1 were highly expressed in subgroup A osteomyelitis." (PMID 36544487, 2022). "Between the two m6A subtypes from the validation group, the expression of 2 collagen-related genes was significantly different, with COL8A2 and COL18A1 both highly expressed in cluster A osteomyelitis." (PMID 36544487, 2022).
Pierson syndrome (1 paper, 2025). Pierson syndrome is characterized by the association of congenital nephrotic syndrome and ocular anomalies with microcoria. "The causative genes linked to the Knobloch, Marfan, and Pierson syndromes are COL18A1, FBN1, and LAMB2, respectively." (PMID 40725504, 2025).
pulmonary hypertension (1 paper, 2025). Increased pressure within the pulmonary circulation due to lung or heart disorder. "In Down syndrome, the overexpression of genes located on chromosome 21—particularly those involved in angiogenesis inhibition, such as COL4A3, endostatin (COL18A1), and RCAN1—is known to contribute to vascular immaturity, pulmonary hypoplasia, and increased risk for pulmonary hypertension." (PMID 41462807, 2025).
sarcoma (1 paper, 2021). A usually aggressive malignant neoplasm of the soft tissue or bone. "The Rb1 nullizygous sarcomas had a significantly lower number of tumors expressing COL18A1, COL4A1, and PLOD2." (PMID 33708626, 2021). "In general, murine sarcomas with Rb1 nullizygosity were associated with the undifferentiated morphology, except for one case identified as aRMS which also showed lower expression of COL18A1, COL4A1, and PLOD2 compared to Rb1 wildtype sarcomas (p = 0.0035, 0.04, and 0.08, respectively)." (PMID 33708626, 2021).
squamous carcinoma (1 paper, 2019). "Additionally, a 3D culture system using human squamous carcinoma cells (TR146) was used to evaluate and correlate the changes in the expression of type XVIII collagen gene, COL18A1, and epithelial keratinization-related markers, e.g., keratin 1 (KRT1) and 10 (KRT10)." (PMID 31554264, 2019).
tendinopathy (1 paper, 2025). "In line with aberrant matrix turnover generally featured in tendinopathy, the transcripts of the following genes were significantly increased in the tendinopathic samples: COL1A1, COL1A2, COL18A1." (PMID 39918402, 2025).
tuberculosis (1 paper, 2021). A chronic, recurrent infection caused by the bacterium Mycobacterium tuberculosis. "The role of collagen type XVIII alpha 1 chain (COL18A1) in anti‐tuberculosis drug‐induced hepatotoxicity (ATDH) has not been reported." (PMID 33296124, 2021).
vision disorder (1 paper, 2021). Any impairment to the vision. "COL18A1 was associated with elevated PSD, and lower VFI and MD reinforcing the importance of collagens in vision disorders." (PMID 33808966, 2021).